KRT34 (keratin 34)
Synonyms: K34; HHA4; KRTHA4; Ha-4; HA4
Tractability: PROTAC: ubiquitination databases record sites on it.
Gene: Protein-coding gene on chromosome 17 (41,377,669 to 41,382,306, reverse strand). Ensembl gene ENSG00000131737.
Subcellular location (Human Protein Atlas): Cytosol; End piece; Principal piece; Equatorial segment; Mid piece
Pathways (Reactome):
Developmental Biology: Formation of the cornified envelope; Keratinization
Gene Ontology:
Molecular function: protein binding; structural constituent of skin epidermis; structural molecule activity
Biological process: epidermis development; epithelial cell differentiation; intermediate filament organization; morphogenesis of an epithelium
Cellular component: extracellular region; cytoskeleton; cytosol; keratin filament
Genetic constraint (gnomAD): Loss-of-function variants: 33 observed, 44.66 expected, observed/expected ratio (o/e) 0.74, 90% interval 0.56 to 0.99. The upper end of that interval is the gene's LOEUF score, 0.99, which puts it in group 4 of 6, group 1 being the genes least tolerant of losing a copy. Missense variants: 521 observed, 508.22 expected, observed/expected ratio (o/e) 1.03, 90% interval 0.95 to 1.1. Synonymous variants: 219 observed, 219.65 expected, observed/expected ratio (o/e) 1, 90% interval 0.89 to 1.12.
Homologues: Orthologues: chimpanzee KRT34 (99% identical), macaque KRT34 (96% identical), rabbit KRT34 (88% identical), rat Krt34 (88% identical), mouse Krt34 (87% identical). Paralogues in human: KRT33A (90% identical), KRT31 (89% identical), KRT33B (89% identical), KRT35 (69% identical), KRT36 (69% identical), KRT32 (68% identical), KRT40 (62% identical), KRT38 (60% identical), KRT39 (60% identical), KRT37 (59% identical), KRT14 (49% identical), KRT15 (48% identical), and 56 more.
Diseases named in the same sentence as KRT34 in open-access papers:
KRT34 is named in the same sentence as 12 diseases in open-access papers, as found by Europe PMC text mining. Sharing a sentence is not in itself a finding about the gene and the disease. The quoted sentences say what the papers report.
prostate carcinoma (3 papers, 2015 to 2025). A carcinoma that arises from epithelial cells of the prostate gland. "Conversely, in the other study, KRT8, KRT15, KRT19, KRT34, and KRT80 were found to be enriched in African American prostate cancer samples." (PMID 40104216, 2025). "KRT34 and KRT80 expression levels were too low or were hardly detected in all the prostate cancer cell lines (Data not shown)." (PMID 36033462, 2022).
bacterial infections (1 paper, 2023). "The downregulated proteins were related to the reduction in markers of inflammation (e.g., Alox5, Lbp, C5, Il36b, and Mmp8) and bacterial infections (e.g., Masp2, Mbl1, Krt34, and Cfd)." (PMID 38030636, 2023).
tumor (1 paper, 2025). "The four most significantly downregulated genes in COM, compared to healthy tissue controls, were all keratin genes (KRT33A, KRT86, KRT34, and KRT38), which is consistent with a potential loss of epithelial differentiation, a hallmark of aggressive tumor behavior." (PMID 40647405, 2025).
KRT34 also shares sentences with these, for which no sentence is quoted: breast carcinoma (1 paper); cancer (1); influenza (1); iron-deficiency (1); lysosomal storage disease (1); melanoma (1); periodontitis (1); staphylococcus aureus infection (1); type 2 diabetes (1).